KRT23 (keratin 23)
Diseases named in the same sentence as KRT23 in open-access papers (continued):
Sharing a sentence is not in itself a finding about the gene and the disease.
prostate carcinoma (1 paper, 2025). A carcinoma that arises from epithelial cells of the prostate gland. "Our study reveals that SLC14A1, ARHGEF38, NEFH, MSMB, KRT23, and KRT15 are potential diagnostic biomarkers for prostate cancer, among which MSMB may play a protective role in prostate cancer." (PMID 40260298, 2025). "We found that the genes SLC14A1, MSMB, KRT23, and KRT15 are primarily enriched in “prostate cancer” signaling pathway." (PMID 40260298, 2025).
rectal cancer (1 paper, 2019). A primary or metastatic malignant neoplasm that affects the rectum. "This led to the identification of genes with increased H3K27ac, i.e., RIPK2, FOXQ1, KRT23, and EPHX4, which were also highly upregulated in primary rectal cancer in an independent dataset." (PMID 31404997, 2019).
steatosis (1 paper, 2012). Increased lipid within the cytoplasm of cells. "Furthermore, we describe the highly significant overexpression of KRT23 in steatohepatitis compared to steatosis and normal liver." (PMID 23071592, 2012). "The most striking examples in this respect were KRT23 and AKR1B10, which we found to be highly differentially expressed in steatohepatitis compared to steatosis and normal liver." (PMID 23071592, 2012).
cancer (22 papers, 2012 to 2025). A tumor composed of atypical neoplastic, often pleomorphic cells that invade other tissues. "An association has been established between KRT23 and Smad4 in malignant cells, promoting Smad4-dependent upregulation and subsequent migration of cancer cells." (PMID 34885040, 2021). "Taken together, these studies suggest that the underlying mechanism of KRT23 in cancers requires in-depth exploration." (PMID 33204716, 2020). "Growing evidence has demonstrated the underlying mechanism of tumorigenesis and migration of KRT23 in different types of cancers." (PMID 33204716, 2020). "Specifically, KRT23 was reported to affect the structural integrity of epithelial cells and to trigger cellular signaling leading to the onset of cancer." (PMID 39771533, 2024). "Evidence from previous studies has indicated that KRT23 influences the proliferation, migration, and prognosis of cancer." (PMID 36092911, 2022). "Pan-cancer analysis revealed that KRT23 has a higher expression in tumor tissues in most types of cancers." (PMID 35814465, 2022). "KRT23 is localized in the Golgi apparatus in the cytoplasm and is involved in the development and migration of various types of human cancers." (PMID 34885040, 2021). "Consequently, we have examined the KRT23 expression in CRC using public cancer OMICS data from an online repository." (PMID 39771533, 2024). "Recently, KRT23 has been reported as a cancer stem cell (CSC) marker; however, its function in the skin is still unknown." (PMID 34639148, 2021). "In addition, KRT23 was also reported to be involved in the development and migration of various types of human cancers." (PMID 33204716, 2020). "KRT23 promoted cancer stem cell properties and increased the expression of CD133 and CD44." (PMID 28749462, 2017). "Furthermore, we intended to identify downstream target genes and associated pathways upon KRT23 knockdown, to elucidate the impact of KRT23 depletion on the molecular and cellular functions of cancer cells." (PMID 24039993, 2013). "In order to evaluate the KRT23 expression in patients with CRC, we used the TCGA and GTEx databases containing public cancer sequencing data." (PMID 39771533, 2024). "Several KRT genes, including the phylogenetically older KRT8, KRT18, KRT19, KRT23, KRT79, KRT80 and KRT222, were found to be differentially expressed in diverse types of cancers." (PMID 36949761, 2023). "Several members of the KRT gene family, including the evolutionarily older KRT8, KRT18, KRT19, KRT23, KRT79, KRT80 and KRT222, were shown to be differentially regulated in diverse cancer types." (PMID 36949761, 2023). "We identified 559 cancer cells according to epithelial and cancer markers including KRT19, KRT7, EPCAM, SOX9, and KRT23." (PMID 34326696, 2021). "This technique identified cell clusters that, through marker genes, included cancer cells—markers EpCAM, KRT8, KRT18, and KRT23, fibroblasts—marker COL1A1 (cancer cells, 4389 cells; fibroblasts, 2549 cells)." (PMID 34026600, 2021). "Both KRT23 and hTERT were highly expressed in CRC tissues compared with their adjacent non-cancer tissues." (PMID 28749462, 2017). "Since then, increasing evidence has shown the pro-cancer properties of KRT23 in certain tumors, although its role has not been comprehensively studied." (PMID 39771533, 2024). "Similarly, immunohistochemical staining revealed that both KRT23 and hTERT were highly expressed in CRC tissues compared with the adjacent non-cancer tissues." (PMID 28749462, 2017). "To confirm the correlation between KRT23 and hTERT and their biological and clinicopathologic significance in CRC patients, we first measured KRT23 and hTERT expression in CRC tissues and their corresponding adjacent non-cancer tissues by western blot." (PMID 28749462, 2017). "However, the carcinogenic role of KRT23 in OC has not been elucidated, and its potential mechanism in cancer remains unclear." (PMID 33204716, 2020).
tumor (18 papers, 2011 to 2025). "Due to this cellular response KRT23 was associated with a potential role as a tumor suppressor in this subset of colorectal cancers." (PMID 21492476, 2011). "KRT23 was upregulated in HBV tumor tissue (logFC = 1.74, p = 0.022) and downregulated in HCV tumor tissue (logFC = −1.54, p = 0.00095)." (PMID 39005337, 2024). "To explore how KRT23 affected immune cell infiltration, we used cytometric bead arrays to detect the chemokines derived from tumor cells with KRT23 knockdown." (PMID 35814465, 2022). "Univariate analysis of gene expression data on tumor aggressiveness (NMIBC versus MIBC) using logistic regression showed genes, including CDKN2A, CTSV, FOXM1, and KRT23, were predictive of tumor aggressiveness." (PMID 34885040, 2021). "The results of univariate analysis demonstrate that CDKN2A, CTSV, FOXM1 and KRT23 were predictive of tumor aggressiveness (MIBC) and the odds of having MIBC was increased by 3% per unit increase of CDKN2Aa (p = 0.01)." (PMID 34885040, 2021). "Of the 154 patient tumor tissue samples, ~91 (59.1%) patients had high expression of both KRT23 and hTERT." (PMID 28749462, 2017). "In summary, our findings are the first to show that KRT23 is a novel hTERT promoter-regulating protein that has an important role in hTERT overexpression and tumor growth in CRC." (PMID 28749462, 2017). "As it is well known that the expression profiles of keratins change significantly during tumor progression and the consequences of these changes have dramatic effects on the morphology of the cells, we chose to study KRT23 further." (PMID 21492476, 2011). "Similarly, the knockdown of KRT23, a member of the keratin family, decreases proliferation and affects the DNA damage response of tumor cells by rendering them more sensitive to ionizing radiation." (PMID 38339228, 2024). "Moreover, many of these genes are associated with stemness, such as MUC5B, as well as tumor biology, including REG4, LYZ, EREG, KRT23, and RAMP1, which were also identified in a previous CRC single-cell study." (PMID 39350339, 2024). "By contrast, KRT23 inhibition significantly inhibited tumor cell growth in vitro and in vivo." (PMID 28749462, 2017). "In contrast, KRT23 is a differentiation marker in MSS CRCs and has a tumor suppressive function in MSI-H CRC." (PMID 40140561, 2025). "Knockdown of KRT23 expression in tumor cells resulted in increased secretion of CCL5 and inhibited tumor cell proliferation." (PMID 35814465, 2022). "Our results revealed that, compared to para-cancerous tissues, the expression levels of SLC14A1, NEFH, MSMB, KRT23, and KRT15 were significantly downregulated in PCa tumor tissues, while ARHGEF38 expression was notably upregulated, consistent with our initial predictions." (PMID 40260298, 2025). "Specifically, the tumor-suppressive role of miR-195-5p in CRC has been demonstrated, revealing it as a critical regulator of multiple cellular processes and identifying γ-catenin (JUP), keratin 23 (KRT23), and pinin (PNN) as its major downstream targets." (PMID 40871106, 2025). "Our comparison of two DCIS regions in Sample #1 reveals reduced myoepithelial markers KRT15, KRT23, and ALDH1A3 and increased invasive markers in DCIS #2 which could indicate a higher grade tumor." (PMID 38114474, 2023). "Promoter methylation correlated with absent expression, while increased KRT23 expression in tumor samples correlated with promoter hypomethylation, as confirmed by bisulfite sequencing." (PMID 24039993, 2013). "First, we did not explore the effect of KRT23 on migration or apoptosis of tumor cells." (PMID 35814465, 2022). "Thus, we sought to not only confirm the differential expression of RIPK2, FOXQ1, KRT23 and EPHX4 in the investigated tumor samples, but also examine whether the differential epigenetic marking of the genes was, indeed, specific for tumor cells and not from stromal contamination." (PMID 31404997, 2019).
infection (2 papers, 2017 to 2019). The state of being infected such as from the introduction of a foreign agent such as serum, vaccine, antigenic substance or organism. "The expression of the majority of the analyzed KRTs was slightly affected, but intriguingly, we observed a specific induction of KRT23 expression 72 h post-infection." (PMID 31216713, 2019). "Subsequently, we collected patient plasma of HCV-infected patients before the start of DAA treatment and after clearance of the infection and analyzed the KRT23 levels by immunoblotting." (PMID 31216713, 2019). "We observed a two-fold increased luciferase activity in cells ectopically expressing KRT23 at 24 h and 48 h post-infection, indicating a proviral effect of elevated KRT23 levels." (PMID 31216713, 2019). "The mRNA and protein expression levels of KRT23 and hTERT were both increased in cells treated with KRT23 lentivirus (the infection efficiency of the lentiviruses was almost 100% at 108 TU/ml)." (PMID 28749462, 2017). "First, we examined the infection efficiency of lentiviruses for KRT23 overexpression." (PMID 28749462, 2017). "Forty eight hours post-infection, the viral titer yielded 1 × 104 TCID50/mL in Jc1-infected PHH, and HCV copy numbers and KRT23 mRNA expression levels were quantified by RT-qPCR." (PMID 31216713, 2019).
adenocarcinoma (1 paper, 2013). A common cancer characterized by the presence of malignant glandular cells. "Promoter binding analysis identified several genes correlating with KRT23 expression in adenocarcinomas." (PMID 24039993, 2013). "Array based methylation profiling of 40 colon samples showed that the promoter of KRT23 was methylated in normal colon mucosa, while hypomethylated in most adenocarcinomas." (PMID 24039993, 2013).
KRT23 also shares sentences with these, for which no sentence is quoted: osteoporosis (6 papers); pancreatic cancer (5); asthma (1); cervical cancer (1); chronic gastritis (1); chronic hepatitis C (1); COVID-19 (1); gastritis (1); gastrointestinal tumor (1); hepatitis C (1); idiopathic juvenile osteoporosis (1); metastatic carcinoma (1); osteoarthritis (1); portal hypertension (1).